CHST10 (carbohydrate sulfotransferase 10)
Description:
Catalyzes the transfer of sulfate from 3'-phosphoadenylyl sulfate (PAPS) to position 3 of terminal glucuronic acid of both protein- and lipid-linked oligosaccharides. Participates in biosynthesis of HNK-1 carbohydrate structure 3-O-sulfo-beta-D-GlcA- (1->3)-beta-D-Gal-(1->4)-D-GlcNAc-R, a sulfated glucuronyl-lactosaminyl residue carried by many neural recognition molecules, which is involved in cell interactions during ontogenetic development and in synaptic plasticity in the adult. May be indirectly involved in synapse plasticity of the hippocampus, via its role in HNK-1 biosynthesis. Sulfates terminal glucuronyl residue of the laminin globular (LG)-domain binding epitope on DAG1/alpha-dystroglycan and prevents further polymerization by LARGE1 glycosyltransferase. Likely defines the chain length of LG epitope, conferring binding specificity to extracellular matrix components. Plays a role in down-regulating the steroid hormones. Sulfates glucuronidated estrogens and androgens with an impact in hormone cycle and fertility. Has a preference for glucuronyl moiety at the 3-hydroxyl group of a sterol ring rather than the 17-hydroxyl group, showing high catalytic efficiency for 17beta-estradiol 3-O-(beta-D-glucuronate) and dehydroepiandrosterone 3-O-(beta-D-glucuronate) hormones.
Synonyms: HNK-1ST; HNK1ST
Tractability: Antibody: UniProt predicts a signal peptide or a membrane-spanning region. PROTAC: ubiquitination databases record sites on it; its protein half-life has been measured.
Gene: Protein-coding gene on chromosome 2 (100,391,860 to 100,417,826, reverse strand). Ensembl gene ENSG00000115526.
Subcellular location: Golgi apparatus membrane
Subcellular location (Human Protein Atlas): Cytosol
Pathways (Reactome):
Metabolism of proteins: Matriglycan biosynthesis on DAG1; Reactions specific to the complex N-glycan synthesis pathway
Gene Ontology:
Molecular function: sulfotransferase activity; HNK-1 sulfotransferase activity
Biological process: androgen metabolic process; estrogen metabolic process; cell adhesion; protein O-linked glycosylation; proteoglycan biosynthetic process; carbohydrate biosynthetic process; glycoprotein biosynthetic process
Cellular component: Golgi apparatus; Golgi membrane; membrane
Genetic constraint (gnomAD): Loss-of-function variants: 24 observed, 36.05 expected, observed/expected ratio (o/e) 0.67, 90% interval 0.48 to 0.94. The upper end of that interval is the gene's LOEUF score, 0.94, which puts it in group 3 of 6, group 1 being the genes least tolerant of losing a copy. Missense variants: 402 observed, 474.56 expected, observed/expected ratio (o/e) 0.85, 90% interval 0.78 to 0.92. Synonymous variants: 161 observed, 179.16 expected, observed/expected ratio (o/e) 0.9, 90% interval 0.79 to 1.02.
Homologues: Orthologues: chimpanzee CHST10 (99% identical), macaque CHST10 (97% identical), dog CHST10 (93% identical), guinea pig CHST10 (92% identical), mouse Chst10 (91% identical), pig CHST10 (91% identical), rat Chst10 (90% identical), rabbit CHST10 (89% identical), tropical clawed frog chst10 (75% identical), zebrafish chst10 (65% identical). Paralogues in human: CHST8 (30% identical), CHST9 (29% identical), CHST12 (29% identical), CHST11 (29% identical), CHST13 (25% identical), CHST14 (23% identical).
Diseases named in the same sentence as CHST10 in open-access papers:
CHST10 is named in the same sentence as 7 diseases in open-access papers, as found by Europe PMC text mining. Sharing a sentence is not in itself a finding about the gene and the disease. The quoted sentences say what the papers report.
melanoma (5 papers, 2014 to 2020). A malignant, usually aggressive tumor composed of atypical, neoplastic melanocytes. "CHST10 is also known to inhibit the invasiveness of melanoma cells, and BTG4 has anti-proliferative properties." (PMID 28241740, 2017). "For example, RARγ, by regulating the expression of carbohydrate sulfotransferase 10 (CHST10), can suppress melanoma invasion." (PMID 27756432, 2016). "The product of CHST10, carbohydrate sulfotransferase 10, is known to inhibit the invasiveness of melanoma cells." (PMID 24393480, 2014). "Overexpression of CHST3 and CHST11 have been linked to BC aggressiveness, relapse, and development of metastasis; in contrast, downregulation of CHST10 and CHST14 has been linked to invasive melanoma and to late stages of colon cancer progression, respectively." (PMID 32605588, 2020).
colon cancer (3 papers, 2017 to 2025). "The demethylation effect was further supported by the reactivation of several genes silenced by DNA methylation in colon cancer cells, such as MGMT, carbohydrate sulfotransferase 10 (CHST10), and B-cell translocation gene 4 (BTG4), leading to inhibited cancer cell growth." (PMID 41226811, 2025).
dengue (1 paper, 2018). "For dengue fever (DF), we found evidence of significant association with CHST10, AHRR, PPP2R5E and GRIP1 genes, which participate in the xenobiotic metabolism signaling pathway." (PMID 29447178, 2018). "The association of the four genes (CHST10, AHRR, PPP2R5E and GRIP1) from the xenobiotic metabolism signaling pathway with Thai DF patients is the first genetic evidence for its implication in dengue pathogenesis, although functional studies have already indicated this association before." (PMID 29447178, 2018).
osteoporosis (1 paper, 2024). A condition of reduced bone mass, with decreased cortical thickness and a decrease in the number and size of the trabeculae of cancellous bone (but normal chemical composition), resulting in increased fracture incidence. "Thus Chst10 might contribute to bone repair when osteoporosis happens." (PMID 38164361, 2024).
tumor (1 paper, 2018). "Five aberrantly methylated genes (epidermal growth factor, EGF; carbohydrate sulfotransferase 10, CHST10; ependymin related 1, EPDR1; bone marrow stromal antigen 2, BST2; and Rac family small GTPase 3, RAC3) were further verified in CRC tumor tissues." (PMID 30360391, 2018).
CHST10 also shares sentences with these, for which no sentence is quoted: breast carcinoma (1 paper); cancer (1).